IL17A (interleukin 17A)
Diseases named in the same sentence as IL17A in open-access papers (continued):
Sharing a sentence is not in itself a finding about the gene and the disease.
autoimmune disease (continued). "At present, there are clear clinical applications of successful IL-17A target therapy standards for the treatment of autoimmune diseases." (PMID 40028265, 2025). "The IL-17 family, comprising six structurally similar members (IL-17A to IL-17F), has garnered substantial research attention given the well-characterized proinflammatory role of its prototypical member IL-17A in autoimmune diseases." (PMID 41007866, 2025). "IL-17A is a pro-inflammatory cytokine that significantly contributes to the pathogenesis of autoimmune diseases, including multiple sclerosis (MS)." (PMID 40924614, 2025). "We provide insights into the potential therapeutic implications of targeting IL-17A and its ubiquitination pathways in inflammatory diseases and autoimmune disorders." (PMID 40821838, 2025). "Clinically, IL-17A inhibitors (e.g., Secukinumab) are already approved for autoimmune disorders, suggesting rapid repurposing possibilities." (PMID 40867579, 2025). "MLN4924 has potential to attenuate IL-17A-induced autoimmune diseases by reducing the secretion of various inflammatory cytokines, including IL-1β, IL-6, TNF-α, and MCP-1." (PMID 40040717, 2025). "Interleukin-17A (IL-17A) is a pro-inflammatory cytokine that plays a pivotal role in immune responses, particularly in the pathogenesis of various autoimmune diseases and infections." (PMID 40821838, 2025). "IL-17A is involved in allergies, autoimmune diseases, and can mediate protective innate immunity against pathogens." (PMID 40369753, 2025). "IL-17A’s pro-inflammatory properties are essential for host protection, but unchecked IL-17 signaling can lead to immunopathology, autoimmune diseases, and cancer progression." (PMID 40005956, 2025). "Targeted modulation of ubiquitin-related enzymes within the IL-17A pathway holds tremendous promise for the treatment of autoimmune disorders." (PMID 40821838, 2025). "Specifically, while IL-17A inhibitors (e.g., Secukinumab) are clinically used for autoimmune diseases, their application in stroke remains confined to animal studies." (PMID 40746532, 2025). "Novel therapies targeting IL-17A signaling have been approved for the treatment of autoimmune diseases and have shown promise in both animal models and human studies of hypertension." (PMID 40028265, 2025). "IL-17A signaling has been reported to facilitate the migration and activation of innate immune cells, such as neutrophils, during infections and autoimmune disorders." (PMID 40632810, 2025). "In human medicine, IL-17a has attracted considerable attention for its proinflammatory role in autoimmune diseases." (PMID 41310729, 2025). "Astrocytes itself can also produce IL-17A, thereby contributing directly to local neuroinflammation, particularly in neuroinflammatory autoimmune disease such as MS." (PMID 40469524, 2025). "Contrary to its potentially beneficial effects in counteracting bacterial and fungal infections, IL-17A is believed to be involved in the pathogenesis of various autoimmune diseases." (PMID 38638687, 2024). "Inhibition of IL-17A pathway via secukinumab, etc. has been used in treatment of these autoimmune diseases." (PMID 38587715, 2024). "On the other hand, several studies have shown that IL-17A can also contribute to the development of tissue damage produced by diverse pathological conditions, such as autoimmune diseases, liver and kidney diseases, and chronic bacterial infection." (PMID 39024223, 2024). "They express IL-17A, a pro-inflammatory cytokine involved in the pathogenesis of autoimmune diseases, with a subpopulation expressing IL-17 in active lesions." (PMID 39273535, 2024). "IL-17 family members include six cytokines (IL-17A through IL17F) that are classically established as inflammatory actors of autoimmune diseases and whose role in wound healing is progressively being investigated." (PMID 39064129, 2024).
autoimmune disease (continued). "The regulatory effect of HMGB1 on IL‐17A expression and function has been reported in some inflammatory and autoimmune diseases by the HMGB1‐Toll‐like receptor 4 (TLR4)‐interleukin (IL)‐23‐IL‐17A pathway." (PMID 38414294, 2024). "Studies have reported a positive correlation between MIF and Th17 cells in autoimmune diseases, and IL-17A expression is impaired in MIF knockout mice." (PMID 39614150, 2024). "Our previous studies in patients with autoimmune diseases documented the important role of the SNPs located within genes coding for IL-17A, IL-17F cytokines as well as their IL-17RA and IL-17RC receptors." (PMID 38792460, 2024). "Initial studies with IL-17A-targeting drugs aim to halt or reduce the production of both Th17 lymphocytes and IL-17, potentially halting the development of autoimmune diseases." (PMID 38999993, 2024). "Th17 cells secrete IL-17A, stimulating proinflammatory molecule secretion and further participating in autoimmune disease pathogenesis." (PMID 38466881, 2024). "IL-17a is highly conserved during the evolution of the vertebrate immune system and plays an important role in infection and autoimmune diseases." (PMID 38993386, 2024). "IL‐17A is a major pro‐inflammatory cytokine produced by Th17 cells, and plays a key role in the development of several autoimmune diseases." (PMID 39429876, 2024). "Although the main source of IL-17A is the Th17 CD4+ cell population, when autoimmune disorders occur, γδ T cells also contribute to the production of IL-17A." (PMID 39063202, 2024). "IL‐17RA is the receptor for IL‐17A, which protects cells from invasion by pathogens and promotes pathological inflammation in autoimmune diseases." (PMID 39355508, 2024). "In terms of functionality, IL‐17A plays a contributory role in the pathogenesis of autoimmune disorders, encompassing conditions such as systemic lupus erythematosus, multiple sclerosis, rheumatoid arthritis, inflammatory bowel disease, and psoriasis." (PMID 38585232, 2024). "Increasing evidence has shown that Th17 cells secrete several types of cytokines (such as IL-17A and IL-6) to exert pro-inflammatory effects in autoimmune diseases, including asthma." (PMID 38579176, 2024). "In allergic and autoimmune diseases, a correlation has been shown between patients’ anxiety levels and IL-17A." (PMID 38067176, 2023). "If so, it would be a beneficial phenomenon, distinguishing PA from other autoimmune diseases in which an increase in IL-17A (as well as in IL-22, IL-23) activity is observed." (PMID 37269464, 2023). "Th17 cells are the main source of IL-17A and are involved in the pathogenesis of autoimmune diseases, including multiple sclerosis, systemic lupus erythematosus, and inflammatory bowel disease." (PMID 38007487, 2023). "Current studies have confirmed that γδT cells-mediated immune response and the IL-17A produced by γδT cells play a key regulatory role in many infectious or autoimmune diseases." (PMID 37600023, 2023). "Cells that co-express IL-17A and IFNγ are more cytotoxic and potent and have been identified in a number of autoimmune diseases (43, –, 45)." (PMID 37615438, 2023). "Supporting our findings, studies have shown that sex hormones (e.g., estrogen and progesterone) promote IL-17A production in Th17 cells, linking to the sex bias of Th17-related immune pathologies such as autoimmune disease and Candida infection." (PMID 38134621, 2023). "Interleukin-17A (hereafter IL-17) is a pro-inflammatory cytokine involved in the immune response to many pathogens and appears to play a role in certain chronic and autoimmune diseases." (PMID 37799720, 2023). "Interleukin 17A and its receptor IL17RA play a pathogenic role in many inflammatory and autoimmune diseases and IL17RA contributes to the inflammatory response by inducing recruitment of innate immune cells." (PMID 37359548, 2023).
autoimmune disease (continued). "Treatment with antibodies that neutralize IL-17A and IL-17F (anti-IL-17A/F) is currently used as a therapy for patients with inflammatory and autoimmune diseases such a psoriasis." (PMID 37291218, 2023). "As an important pro-inflammatory factor, IL-17A is secreted mainly by Th17 cells and is closely related to many diseases, including autoimmune diseases." (PMID 37446715, 2023). "Interleukin-17A (IL-17A) is a major mediator of tissue inflammation in many autoimmune diseases and we have previously shown that this cytokine induces autoimmune carditis in the Lewis rat model of rheumatic heart disease." (PMID 36739443, 2023). "Main characteristics of the immune cell populations secreting IL-17A and IL-17F and their role in autoimmune diseases." (PMID 37600764, 2023). "Interleukin-17A (IL-17) is a pro-inflammatory cytokine involved in the immune response to many pathogens playing also a role in certain chronic and autoimmune diseases." (PMID 37799720, 2023). "General, well-described effector functions of IL-17A in autoimmune diseases are induction of inflammatory mediators from keratinocytes and fibroblasts." (PMID 36857006, 2023). "IL17A is a pro-inflammatory cytokine produced by Th17 cells that can drive inflammatory pathology during infection and autoimmune diseases." (PMID 37781522, 2023). "The role interleukin-17A (IL-17A) plays in autoimmune disease is interesting as this cytokine is richly expressed in nociceptive neurons." (PMID 36833753, 2023). "Therapeutic targeting of the Th17 cell pathway or blocking of IL-17A has been proved effective in several autoimmune diseases, but ineffective in IBD." (PMID 34983626, 2022). "Rationale: GLK (MAP4K3) activates PKCθ-IKKβ axis in T-cell activation and induces IL-17A-mediated autoimmune diseases." (PMID 35966593, 2022). "The proinflammatory role of IL-17A in autoimmune diseases has drawn much attention over the past decades." (PMID 36350619, 2022). "Despite many other studies with probiotics focused on IL-1 β expression during treatment in AA, we have chosen to focus on IL-17A instead, as this cytokine is specific for autoimmune diseases." (PMID 36615489, 2022). "In conclusion, this review presents evidence of the ability of IL-17A to drive the development and exacerbation of clinical manifestations in three major autoimmune diseases." (PMID 35620115, 2022). "IL-17A is an essential player in host disease defense; aberrant expression of IL-17A can lead to many autoimmune diseases and cancers." (PMID 35185884, 2022). "At present, IL-17A has been observed under different tissues and immunopathological conditions, such as autoimmune diseases, tumors or obesity." (PMID 35392087, 2022). "Under the stimulation and activation of antigens, Th17 cells secret proinflammatory factors—for example IL-17A, which participates in the peripheral inflammation of autoimmune diseases." (PMID 36430328, 2022). "IL-17A is an important cytokine secreted by T-helper-17 cells in chronic inflammatory and autoimmune disease conditions." (PMID 35465355, 2022). "RA is an autoimmune disorder of the joints in which proinflammatory cytokines, such as TNFα, IL-17A, immune cells and fibroblast-like synoviocytes, attack joints and cause bone deformation." (PMID 35784351, 2022). "Given its role in mediating IL-17A-induced responses, CMTM4 represents a potential new target for the therapy of IL-17A-mediated autoimmune diseases." (PMID 36271145, 2022). "Current inhibitors of IL-17A, including anti-IL-17A monoclonal antibodies seckinumab, ixekizumab, and bimekizumab, have been approved for the treatment of autoimmune diseases such as psoriatic arthritis and ankylosing spondylitis." (PMID 35935949, 2022). "On the other hand, dysregulated IL-17A production and/or signaling can trigger chronic inflammation and tissue damage, eventually leading to the development of autoimmune disorders or malignant transformation." (PMID 36271145, 2022).
autoimmune disease (continued). "IL-17A are important for hyper sensitivities and autoimmune diseases, and it has been reported that IL-17A promotes mouse EAE." (PMID 34819358, 2022). "RORC is required for IL-17A production from Th-17 cells, which plays a crucial role in the pathogenesis of several inflammatory and autoimmune diseases." (PMID 36776357, 2022). "IL-17A is a pro-inflammatory cytokine secreted explicitly by Th17 cells, which can induce a robust inflammatory response and contributes to a variety of autoimmune diseases." (PMID 35898466, 2022). "Th17 cells play a key role in the development of autoimmune disease by producing the proinflammatory cytokines IL-17A." (PMID 36601077, 2022). "IL17A and IL17F, cytokines of the IL17 family, are evolutionarily highly conserved cytokines associated with autoimmune diseases." (PMID 35546404, 2022). "In the mid-2000s, an important role was attributed to these IL-17A and IL-17F producing lymphocytes in the context of autoimmune diseases." (PMID 35301281, 2022). "Many studies have shown that serum interleukin-17A (IL-17A) plays a key role in various infectious diseases, autoimmune diseases, and cancers." (PMID 36119497, 2022). "Despite the main source of IL-17A being Th17 CD4+ αβ T cells, γδ T cells also contribute to IL-17A production in autoimmune diseases." (PMID 36499125, 2022). "IL-17A is a key biomolecule in various infectious diseases, inflammatory disorders, autoimmune diseases, and cancers." (PMID 36119497, 2022). "So far, only IL-17A and IL-17F have been found to be related to the occurrence of autoimmune diseases, and the functions of the remaining IL-17 family members are still unclear." (PMID 36133744, 2022). "Interleukin 17A (IL-17A), a member of the IL-17 family, has been proven to play crucial roles in not only autoimmune disorders but also viral infectious diseases." (PMID 34504501, 2021). "Increased levels of IL-17A have been reported in autoimmune diseases; however, IL-17A also plays a role in neonatal host defense and immunity, particularly in the defense against extracellular pathogens and fungal microbes." (PMID 33983993, 2021). "The levels of Il-17A, which is a pro-inflammatory cytokine engaged in the pathogenesis of various autoimmune disorders, were increased at 8 h after ConA administration, and GRMS-55 decreased the concentrations of this cytokine at both dose levels." (PMID 33919375, 2021). "Interleukin 17A and its receptor IL17RA play a pathogenic role in many inflammatory and autoimmune diseases, such as rheumatoid arthritis." (PMID 35082796, 2021). "We have previously shown that both anti-CD28 and soluble TNFα inhibited the expression of PTPN22, a gene that is associated with several autoimmune diseases, but only anti-CD28 promoted the production of IL-17A/F in anti-CD3 stimulated PBMCs." (PMID 34301319, 2021). "IL-17A plays a critical role in neutrophil recruitment, angiogenesis, inflammation, and autoimmune diseases." (PMID 34804155, 2021). "Of note, IL17A and IFNγ, two pro-inflammatory factors involved in many autoimmune disorders, were activated in NMO, MS and autoimmune GFAP astrocytopathy." (PMID 34367165, 2021). "An increased level of IL-17A has been detected in BD serum and the IL-23/IL-17 pathway is seen as crucial in several autoimmune diseases such as rheumatoid arthritis that had previously been regarded at Th1 related disease." (PMID 35003055, 2021). "These Th17 cells, which secrete interleukin-17A (IL-17A), IL-17F, IL-22, and IL-26, are thought to play a role in autoimmune diseases, allograft rejection, and inflammatory immune responses." (PMID 33731680, 2021). "Because of the important role of IL-17A and IL-17F in inducing tissue inflammation, Th17 cells have been shown to play a critical role in the etiopathogenesis of many autoimmune diseases, in which Th1 was originally considered as a dominant factor." (PMID 34576041, 2021).
autoimmune disease (continued). "As the main product of Th17 cell, IL-17A plays important roles in autoimmune diseases such as multiple sclerosis, inflammatory bowel disease, and arthritis." (PMID 33981738, 2021). "By the findings of IL17A’s determinant role in diseases, feasibility of targeting IL17A for treating certain autoimmune diseases has been pursued since early 2010s." (PMID 33509093, 2021). "Recently, IL-17A–targeted treatment for the attenuation of autoimmune disease has been achieved by IL-17–blocking antibodies or an IL-17R antagonist." (PMID 33205383, 2021). "In human clinical settings, IL-17A blocking by monoclonal antibody strategies led to a significant improvement in patient care for several inflammatory and autoimmune disease." (PMID 35006414, 2021). "IL-17A (also known as IL-17), secreted by T helper cell type 17 (Th17), is a potent proinflammatory cytokine that plays an important role in the pathogenesis of various autoimmune diseases, including DED." (PMID 34769057, 2021). "The discovery of the key roles of IL-17A and IL-17A-producing cells in inflammation, autoimmune diseases, and host defense has led to the experimental targeting of the IL-17A pathway in different animal models as well as in clinical trials in humans." (PMID 34167455, 2021). "IL-17A production by γδ T cells is involved in antifungal immunity and in the onset of autoimmune disease." (PMID 32987705, 2020). "A high salt diet (HSD) exacerbates IL-17A-induced inflammation in inflammatory bowel disease and other autoimmune diseases." (PMID 33126615, 2020). "In recent reports concerning its function in autoimmune diseases, IL-17A has been shown to drive autoimmune responses by promoting the formation of spontaneous germinal centers and the production of autoantibodies." (PMID 32059488, 2020). "Th17 cells are generally pro-inflammatory, acting via the release of mediators such as IL-17A and IL-22 and play an important role in autoimmune diseases (e.g., Crohn’s disease)." (PMID 33537029, 2020). "Interleukin 17A (IL-17A) and interleukin 17F (IL-17F) appear to play important role in pathogenesis of some autoimmune diseases." (PMID 32724117, 2020). "IL-17A plays a pivotal role in various infectious diseases, inflammatory and autoimmune disorders, and cancer." (PMID 32849528, 2020). "Upregulated IL-17A and IL-17F expressions are found during inflammation, And patients with severe allergies, chronic inflammatory diseases, and autoimmune diseases can have high levels of IL-17." (PMID 32260590, 2020). "Recent studies showed that T cells are involved in a variety of aseptic inflammation and autoimmune diseases in an IL17A-dependent manner." (PMID 32680482, 2020). "As excessive TH17 cell activity is linked to many autoimmune diseases, IL-17C-mediated stimulation of the TH17 cell represents a cause for TH17 autoimmunity upstream of main effector cytokines like IL-17A and F." (PMID 32174926, 2020). "Regarding potential miRNAs involved in Th17/IL-17A pathway regulation, most studies have been carried out in autoimmune diseases." (PMID 32987705, 2020). "IL-17A has a predominant role in the pathogenesis of autoimmune diseases, and therefore in this review we will focus on this member." (PMID 32993066, 2020). "IL-17A is an important cytokine that is involved in the pathogenesis of animal models of autoimmunity and human autoimmune diseases, including SLE." (PMID 33597953, 2020). "In human inflammatory or autoimmune diseases and neurodegenerative diseases, the IL-17A cytokine family has been reported to play a crucial function." (PMID 33132897, 2020). "Several studies showed the importance of IL-17A as a major cytokine that mediates responses in inflammation, infection, and autoimmune diseases through binding to its unique receptor (IL-17RA) and stimulates ACT1 signaling." (PMID 32650733, 2020).